S100B (S100 calcium binding protein B)
Diseases named in the same sentence as S100B in open-access papers (continued):
Sharing a sentence is not in itself a finding about the gene and the disease.
melanoma (continued). "In our study, we aimed to explore the relationship between blood biomarkers in melanoma, such as lactate dehydrogenase (LDH), C-reactive protein (CRP) and S-100B, with imaging-based total tumor burden in metastatic melanoma patients treated with immune checkpoint inhibition." (PMID 35494048, 2022). "PMEL, S100B, SERPINE2, TYR, and PRAME were highly expressed in tumor cells and could be the marker genes for melanoma." (PMID 35646893, 2022). "Mit dem im Serum nachweisbaren Protein „melanoma inhibiting activity“ (MIA) wurde kürzlich ein Marker vorgestellt, welcher in Kombination mit etablierten Markern wie S100B von prognostischer Aussagekraft ist, darüber hinaus aber auch als therapeutisches Target dienen kann." (PMID 34605930, 2022). "S100B, VEGF (vascular endothelial growth factor), IGF-1R (the insulin-like growth factor 1 receptor), Wnt-5a, LDH (lactate dehydrogenase), and MIA (melanoma inhibitory activity) have all been shown to correlate positively with prognosis in CM." (PMID 35982458, 2022). "It is important that S100B inhibitors designed to control malignant melanoma do not block S100A1, ensuring that normal skeletal and cardiac muscle function is retained." (PMID 33450915, 2021). "In some cases, the level of these biomarkers can be used for prognostic purposes—in stage IV melanoma patients, the melanoma biomarkers MIA and S100B are raised and detectable in EVs from their sera; raised levels of these biomarkers are also associated with shorter median survival." (PMID 33145869, 2021). "Furthermore, a small molecule S100B inhibitor, SC0025, which was discovered previously to bind S100B and mediate S100B-dependent killing in melanoma cells was used." (PMID 34411141, 2021). "Studying the reliability of FDG-PET/CT and the serum S-100B assay, the authors found that, while these determinations were reliable (sensitive) for skin-priming melanoma metastases, they were not as reliable in cases of metastasis from uveal melanoma." (PMID 34831313, 2021). "Without this clinical information, rise of S100B and IL-6 would have been interpreted as immune activation against melanoma metastases." (PMID 32188047, 2020). "Although several molecules have some potential clinical values as melanoma biomarkers (lactate dehydrogenase (LDH), tyrosinase, Programmed Cell Death 1 Ligand 1 (PD1L1) and S100B), they also presented some limitations, and for this reason, there is currently no ideal biomarker in melanoma." (PMID 33256110, 2020). "S100A1 is also highly expressed in melanoma tumors, but it differs from S100B in that it is not actively secreted in the serum." (PMID 33256110, 2020). "Although GFP expression was also occasionally detected in the dermis, none of the GFP+ dermal cells expressed melanocyte and/or melanoma markers, including Sox10, S100b, and Nestin 32–34." (PMID 31685822, 2019). "Furthermore, there were no infiltrating tumors found in the lymph nodes and spleen as evidenced by low expression of melanoma markers HMB45 and S‐100B in tissue sections, while staining intensity scoring showed strong agreements with our observations." (PMID 30886812, 2019). "In addition, IHC staining for melanoma markers HMB45 and S‐100B further identifies that malignant tumor cells spread through lymphoid organs from established primary tumor." (PMID 30886812, 2019).
melanoma (continued). "Furthermore, classical melanoma markers human melanoma black (HMB)‐45 and S100 calcium‐binding protein B (S‐100B) diagnosed the same lesions as melanocytic neoplasms." (PMID 30886812, 2019). "S100B is mainly expressed in the brain and is strongly secreted by melanoma cells but is not expressed in colorectal cancer." (PMID 29534068, 2018). "The LIAISON system was primarily designed to detect and screen for S100B in malignant melanoma and other tumors and is thus not designed for quick analyses." (PMID 27957604, 2017). "For example, NO synthase activity is strongly up-regulated in melanoma cell lines, while the concentration of S100B in melanocytic tumor is roughly 100 times higher than in normal skin." (PMID 27159591, 2016). "Kluger and colleagues proposed a multiplex, plasma-based protein biomarker panel that included CEACAM, ICAM-1 (intercellular adhesion molecule 1), osteopontin, MIA (melanoma inhibitory activity), GDF-15 (growth differentiation factor 15), TIMP-1 (tissue inhibitor of metalloproteinase 1), and S100B." (PMID 27642217, 2016). "In stage IV melanoma, only S100-B significantly (not YKL-40) correlates with treatment response and survival." (PMID 26002577, 2015). "Another study brought evidence that circulatory S100B could pinpoint with a better precision than LDH, the poor prognosis in stage IIIB-C melanoma patients." (PMID 32309563, 2015). "For instance, S100B, C reactive protein (CRP), lactate dehydrogenase (LDH), pro-platelet basic protein precursor PPBP and IL-8 may help to determine the prognosis of melanoma patients." (PMID 23533572, 2013). "S100B has probably become the most useful tumor marker in clinical practice but seems limited to advanced stage III and stage IV melanoma patients: in stages I and II S100B does not provide independent prognostic information." (PMID 22287956, 2012). "S100B-concentration in the serum is also modulated by factors independent of melanoma reducing specificity to 85%." (PMID 21935432, 2011). "Whilst S100B, MIA and TA90IC may be useful in assessing prognosis in melanoma, they have not been evaluated as response markers for IFN-adjuvant therapy for melanoma." (PMID 22220281, 2011). "A multivariate analysis revealed that a combination of FDG PET/CT, S100B and MIA did not improve the sensitivity and specificity to detect metastases in high risk melanoma patients." (PMID 21935432, 2011). "Melanoma samples included as positive controls showed intense S100B expression within the malignant cells (data not shown)." (PMID 15280928, 2004). "While S100B is not suitable as a marker in the early stages of the disease, as it is sometimes undetectable in serum, study data indicate its prognostic value in higher stages of melanoma." (PMID 40535809, 2025). "In addition, serum S100B is also used to monitor metastatic melanoma because melanoma metastases produce S100B in some, but not all, patients with melanoma." (PMID 38171113, 2024). "However, in contrast to metastatic patients with BRAF wild-type melanoma, serum S100B was not a prognostic factor for OS in metastatic patients with BRAF mutant melanoma." (PMID 39272837, 2024). "The stage of melanoma did not influence the concentration of exosomes, but patients with advanced stages had a higher content of S100B and melanoma inhibitory activity (MIA) proteins per particle, which could reflect the stage, progression, and metastases." (PMID 34575876, 2021). "Thus, the S100B-dependent inhibition of IL6 expression and secretion into a stress-free microenvironment could facilitate melanoma cells to escape the immune surveillance during melanoma progression." (PMID 34411141, 2021).
melanoma (continued). "Moreover, serum S100B level is increased in patients with melanoma, independent of the cancer stage." (PMID 32295074, 2020). "Nevertheless, S100B as well as IL-6 might not represent the most sensitive and most useful serum or blood markers for the detection of tolerance breakage in melanoma." (PMID 32188047, 2020). "S‐100B cannot exclude recurrent disease during follow‐up of stage III melanoma." (PMID 31468535, 2019). "S‐100B cannot exclude recurrent disease in the follow‐up of stage III melanoma, but might be useful as an extra selection tool in FDG PET/CT scanning for the detection of recurrent disease." (PMID 31468535, 2019). "Melanoma patient sample analysis revealed a strong association of MHA-3 with the tumour site and was able to identify lymph node metastasis, which was not possible with S100b." (PMID 27853253, 2016). "Immunohistochemistry on sections of the removed eyes revealed hyperplasia in the choroid layer, even at this young age, seen as increased abundance of cells expressing the melanoma marker S100B compared to ret−/− non-tumor bearing litter mates, but no tumor nodules were visible." (PMID 25762633, 2015). "However, with patient samples all cells were similar to each other with no clear size distinction between cells positive or negative for melanoma markers (either Melan A or S100B)." (PMID 24811334, 2014). "It is not known whether melanin production in melanoma cells affected serum S100B levels." (PMID 37664072, 2023). "Moreover one should remember that S100B is not melanoma specific and that its serum level can be elevated in healthy subjects, nonmelanoma skin cancer patients, in neurological disorders, in AIDS, in central nervous system tumours, and even in various gastrointestinal cancers." (PMID 22287956, 2012). "The literature also points to evidence suggesting a potential negative correlation between S100B levels, OS, and PFS in melanoma patients, particularly in those with advanced or metastatic disease." (PMID 40535809, 2025). "Documentation of the patient’s performance status at advanced melanoma diagnosis was not always consistent, levels of LDH and S100B were not available of all patients and some pathology reports were unavailable or incomplete." (PMID 40217072, 2025). "Thus, serum S100B may not serve as a reliable marker for the early diagnosis of melanoma." (PMID 38202181, 2023). "A case-control study performed on patients from the Netherlands showed that mean serum concentrations of S-100B and MIA were significantly higher in patients with metastases compared to melanoma patients without metastases." (PMID 37628989, 2023). "Multivariate analysis revealed that S100A8/A9 and S100B, but not LDH, were the only serum markers that independently predicted OS in stage III melanoma." (PMID 33925387, 2021). "There is no blood test that can be used for diagnosis to detect melanoma recurrence, although lactate dehydrogenase (LDH) and S-100B can be useful for monitoring." (PMID 33233603, 2020). "In cutaneous melanomas, Src-1 increases S100β expression by serving as a coactivator for HOXC11, and high expression of Src-1 and HOXC11 was found in malignant melanoma but not in benign nevi." (PMID 30973923, 2019). "Compared with dacarbazine and programmed death 1 (PD‐1) antibody, this treatment in advanced melanoma murine models, achieves a striking curable rate of 90% without melanoma prognostic markers LDH and S‐100B detection, followed by a relapse‐free survival rate of 83.33% in 300 days." (PMID 30886812, 2019). "Unfortunately, however, serum S100B and LDH are not specific for melanoma." (PMID 22291846, 2012).
Stroke (156 papers, 2009 to 2026). Sudden impairment of blood flow to a part of the brain due to occlusion or rupture of an artery to the brain. "Biomarkers such as neurofilament light chain (Nf-L), tau protein, and S100b reflect the extent of brain injury and are associated with secondary neurodegeneration and correlate with worse functional outcomes post stroke." (PMID 40356948, 2025). "NSE and S100β in peripheral blood (PB) can provide valuable and timely diagnostic information for stroke, which is necessary for timely management and decision-making, and is conducive to clinical diagnosis and treatment guidance for stroke patients." (PMID 39669376, 2024). "The highest S100β level was similarly associated with the infarct volume in patients with stroke in either hemisphere (dominant: β 36.853, 95% confidence interval (CI) 22.659–51.048, P < 0.001; non-dominant: β 23.645, 95% CI 10.774–36.516, P = 0.007)." (PMID 39358745, 2024). "Here, it is well known that obesity, liver cirrhosis, migraine, chronic kidney disease, and previous stroke associated with false-positive S100B levels." (PMID 39201780, 2024). "We also found a positive correlation between the levels of circulating S100B and white matter hyperintensities, a predictor of risk of stroke and cognitive impairments." (PMID 38182718, 2024). "Using bivariate correlation analysis, we confirmed that NSE on admission and S100-β level at 48 h of stroke onset was significantly associated with hs-CRP and D-D, respectively." (PMID 39669377, 2024). "MMP-9 associated with D-dimer, BNP and S100b showed good sensitivity in the diagnosis of stroke and the differentiation between the various forms of stroke." (PMID 37511304, 2023). "Studies have shown that S100B is associated with the lesion area of stroke and the degree of inflammation throughout the body." (PMID 36504682, 2022). "The central nervous system damage and the inflammatory response caused by a stroke can stimulate the expression of S100B." (PMID 33959658, 2021). "Abraira concluded that reduced S100B levels were related to a greater risk of epilepsy after stroke." (PMID 33959658, 2021). "The results indicated that old age, a higher NIHSS, and elevated serum levels of sTREM-1 human S100B were associated with a worse stroke outcome." (PMID 33375339, 2020). "A similar study in Han Chinese patients with ischemic stroke found that the A allele was associated with increased risk of stroke as well as elevated serum S100B." (PMID 32379790, 2020). "Cerebrovascular and neuropsychiatric disorders, trauma, and stroke can cause increased serum S100B protein levels due to S100B release from astrocytes." (PMID 32024492, 2020). "This role of S100β protein is associated with the regenerative processes occurring after stroke (e.g., in hippocampus), as well as with postischemic neuroplasticity." (PMID 31701356, 2020). "Higher peak concentrations of MBP, neuron-specific enolase (NSE) and S100B in the serum of patients at 24 h after stroke have been associated with stroke severity and larger infarct volumes." (PMID 31001280, 2019). "Increases in S100β have been associated with neurologic outcomes after cardiac surgery cardiac arrest and stroke." (PMID 29997569, 2018). "It has been suggested that S100A12, S100A8/A9, and S100B are linked to specific diseases and conditions such as auto-inflammatory diseases, stroke, and trauma." (PMID 29379499, 2017). "An association has been described between S100β protein plasma levels and the National Institutes of Health Stroke Score." (PMID 25029344, 2014). "We believe that metabolic investigations such as protein C, protein S, and anti-thrombin deficiency should be done, as well as determining S100β protein levels for post-CABG stroke and cerebral damage." (PMID 24217261, 2013). "Higher S100B levels have been associated with poorer outcomes in stroke patients." (PMID 40142325, 2025).
Stroke (continued). "Elevated S100B levels can indicate neurological complications associated with the disease, such as cognitive impairment, diabetic neuropathy or even an increased risk of stroke." (PMID 41296388, 2025). "Higher levels of copeptin and S-100B on MRI were associated with increased stroke severity, as evidenced by higher National Institutes of Health Stroke Scale (NIHSS) scores, and were predictive of poorer clinical outcomes, including an increased risk of mortality and disability following a stroke." (PMID 39224610, 2024). "Elevated levels of S100B have been observed in neurodegenerative diseases and brain injuries, such as Alzheimer’s Disease, Parkinson’s Disease, Down syndrome, and stroke, where it may act as a damage-associated molecular pattern (DAMP) protein." (PMID 38671467, 2024). "Although the interaction between stroke lateralization and serum S100β levels in predicting infarct volume was significant (Pinteraction = 0.014), the association between S100β levels and infarct volume was similar between patients with either dominant or non-dominant hemisphere stroke." (PMID 39358745, 2024). "In addition, increased concentration of S100B before thrombolytic therapy have been found to be an independent risk factor for hemorrhagic transformation in stroke patients." (PMID 39459548, 2024). "Due to stroke, ischemia and hypoxia occur in the brain, leading to rupture of the membrane structure of the neurons, and the process of acute stroke causes a large release of S100β and NSE into the blood." (PMID 37612344, 2023). "Studies have shown that increased serum levels of S100B are associated with infarct volume, risk of hemorrhagic transformation, and functional outcomes in stroke patients, highlighting its potential as a marker for predicting the development of malignant brain edema." (PMID 37752283, 2023). "Notwithstanding, studies are still conducted on limited cohorts, therefore results need to be consolidated by larger cohorts and longitudinal studies, evaluating the association between S100b changes, volume of tissue damage and the functional or cognitive outcome over the post-stroke phases." (PMID 37719764, 2023). "In ischemic stroke, high levels of S100B have been associated with the degree of systemic inflammation disregarding the size of the infarction, therefore S100B has been proposed as a potential biomarker to predict recovery outcomes after stroke." (PMID 36699006, 2022). "Additionally, a high serum concentration of S100β at 6 h after stroke onset was associated with increased risk of post-stroke infections." (PMID 34168606, 2021). "We assessed whether NF-L, S100B, and IL-6 were associated with clinical severity on admission (Scandinavian Stroke Scale, SSS), diagnosis of ischemic stroke vs. TIA, and functional outcome at 3 months (modified Rankin Scale, mRS)." (PMID 32595585, 2020). "When compared to other thromboinflammatory biomarkers from the literature such as S100B, which has been associated with tissue damage, post-stroke infections and consecutively mortality, CT-pro-ET-1 predicted overall mortality in ischemic stroke patients independently of known risk factors." (PMID 33584523, 2020). "Increased serum S100β levels are implicated in various neurologicaldysfunctions, such as mood disorders, hypoperfusion, poor clinical effects ofintracerebral hemorrhage, and hemorrhagic transformation in thrombolyzed patients withischemic strokes." (PMID 28143956, 2017). "In additon, higher levels of S100β are associated with reduced cognitive function in patients following different types of surgery, brain injury and stroke." (PMID 27199659, 2016). "Furthermore, an elevated serum S100B level has been demonstrated in ischemic stroke and is associated with worse outcome after a stroke." (PMID 27007976, 2016). "In addition, elevated S100B levels have been linked with poor functional outcomes following stroke." (PMID 40949500, 2025).